TNFAIP3 (TNF alpha induced protein 3)
Diseases named in the same sentence as TNFAIP3 in open-access papers (continued):
Sharing a sentence is not in itself a finding about the gene and the disease.
polyarthritis (6 papers, 2013 to 2024). "Mice with an A20 deficiency (Tnfaip3–/– mice) in the myeloid compartment develop spontaneous polyarthritis with sustained proinflammatory cytokine production." (PMID 36633909, 2023). "In a spontaneous polyarthritis model, A20Myel−KO, a myeloid-cell specific deletion of an RA susceptibility gene A20/Tnfaip3 contributed to an enhanced NLRP3 driven caspase-1 activation, pyroptosis, and IL-1β release." (PMID 37598797, 2023). "The TNFAIP3 locus is implicated as a positively associated factor in RA and knockout of TNFAIP3 in mice triggered erosive polyarthritis resembling RA." (PMID 23874885, 2013). "Another important discovery, recently made, is that, in mice with specific deletion in the myeloid cells of the Tnfaip3/A20 gene, there was a development of spontaneous erosive polyarthritis, similar to RA in patients." (PMID 32545788, 2020). "Rare loss-of-function mutations in TNFAIP3 cause the autosomal dominant IEI familial Behçet-like autoinflammatory syndrome-1, an autoinflammatory disorder characterised by systemic inflammation, mucosal ulceration, polyarthritis, uveitis, and recurrent infections in some." (PMID 39241920, 2024).
Sepsis (6 papers, 2007 to 2024). Sepsis is defined as life-threatening organ dysfunction caused by a dysregulated host response to infection. "Subsequently, we further screened two biomarkers, including Gch1 and Tnfaip3, which were associated with cellular responses to bacterial-derived molecules and lipopolysaccharides and were probably the hub molecules in the pathogenesis of sepsis-associated ALI." (PMID 38071255, 2023). "sEVs from patients with sepsis delivered miR-125a-5p to lung macrophages to inhibit Tnfaip3 and delivered miR-221-3p to neutrophils to inhibit Fos." (PMID 38910259, 2024). "In macrophages, the levels of Tnfaip3 decreased significantly in response to sEVs from patients with sepsis (P < 0.01) compared with those from the healthy sEV group." (PMID 38910259, 2024). "Therefore, it is tempting to speculate that SNPs at the TNFAIP3 and TNIP1 genes leading to low expression or malfunction of the corresponding proteins may be associated with the development and/or the outcome of sepsis." (PMID 30813592, 2019). "With regard to apoptosis, both pro-apoptotic (COP1, GADD45B and RIPK2) and anti-apoptotic (TNFAIP3 and BIRC3) genes were induced in the early stages of sepsis." (PMID 17324256, 2007). "The boxplot revealed 26 differentially expressed genes between the sepsis-induced ALI and control samples: Ncf2, Slc2a6, Cd44, Txnip, Slc2a1, Ubc, Hspb1, Zfp36, Arntl, Ddit4, Tnfaip3, Txnrd1, Mt1, Hmox1, Gch1, Gclc, Stat3, Egfr, Hif1a, Bach1, Socs1, Dusp1, Cdkn1a, Fth1, Steap3, and Alox12." (PMID 37081490, 2023). "Finally, several studies have demonstrated the association of both TNFAIP3 and TNIP1 SNPs with multiple chronic inflammatory diseases, but there has not been any study analyzing their relationship with sepsis." (PMID 30813592, 2019).
type 2 diabetes (6 papers, 2009 to 2025). "TNFAIP3 upregulation was associated with the activation of “maturity onset diabetes of the young”, whereas its downregulation correlated with “glycerolipid metabolism” and “nature killer cell mediated cytotoxicity”." (PMID 40646297, 2025). "TNFAIP3 expression is reduced in peripheral blood mononuclear cells (PBMCs) from patients with type 2 diabetes." (PMID 34831306, 2021).
A20 haploinsufficiency (5 papers, 2021 to 2025). Any immune dysregulation disease in which the cause of the disease is a mutation in the TNFAIP3 gene. "Pathogenic variants in TNFAIP3 (A20), on the other hand, cause autoinflammatory diseases such as A20 haploinsufficiency (HA20), which can present diverse autoimmune or inflammatory symptoms that may overlap with or mimic other syndromes." (PMID 41226818, 2025). "Monogenic variants like nonfunctional TNFAIP3 forms lead to early-onset BD-like syndrome (HA20) due to A20 haploinsufficiency." (PMID 38003572, 2023).
autoinflammatory syndrome (5 papers, 2019 to 2022). A group of disorders of the innate immune system characterized by attacks of seemingly unprovoked inflammation without significant levels of either autoantibodies or autoreactive T cells more characteristic of autoimmune disease. "Heterozygous mutation in TNFAIP3 leads to the autoinflammatory syndrome: familial Behcet’s-like disease." (PMID 36064566, 2022). "Diseases associated with TNFAIP3 include autoinflammatory syndrome, especially SLE." (PMID 35120571, 2022). "The present research indicated that the TNFAIP3 mutation of c.436-437deTC (p.L147Qfs∗7) accounted for familial Behcet-like autoinflammatory syndrome in the child suffering from HA20, while no variation in this locus was found in her parents." (PMID 34011076, 2021).
Genital ulcers (5 papers, 2016 to 2025). "TNFAIP3 deficiency typically causes intestinal, oral, and genital ulcers, which are frequently diagnosed as iBD or CD." (PMID 40474095, 2025).
Immunodeficiency (5 papers, 2019 to 2024). Failure of the immune system to protect the body adequately from infection, due to the absence or insufficiency of some component process or substance. "Examples of splice site, frameshift, or nonsense variants in TNFAIP3 associated with A20 haploinsufficiency and other immune diseases." (PMID 39125844, 2024). "In this review, we summarize the immune disease-related mutations described in the coding region of the TNFAIP3 gene, including the phenotypes and disease progression." (PMID 39125844, 2024). "Large deletions in TNFAIP3 associated with A20 haploinsufficiency and other immune diseases." (PMID 39125844, 2024). "Despite promising data indicating that helminths can suppress various immune disorders, our data show that using live helminths also holds great risks, as dominant genetic factors, including Tnfaip3 mutations, can instead promote persistent inflammation in response to helminth infection." (PMID 38680500, 2024). "For example, a patient with autoinflammatory features may require a selection that favors genes associated with proinflammatory diseases such as MEFVand TNFAIP3, whereas a patient with mainly immunodeficiency may have preferential scoring for genes such as BTK and DOCK8." (PMID 31388879, 2019). "Heterologous IKZF mutation in B cell deficiency and autoimmunity, heterologous TNFAIP3 mutation in autoinflammation and immunodeficiency, heterologous IKBKB variant in common variable immunodeficiency, and homozygous TNFSF13 (APRIL) deficiency in plasmacyte defect were reported in the past 5 years." (PMID 33766139, 2021).
Insulin resistance (5 papers, 2020 to 2025). Increased resistance towards insulin, that is, diminished effectiveness of insulin in reducing blood glucose levels. "Consistently, heterozygous TNFAIP3 depletion reversed the improved glucose metabolic abnormalities and insulin resistance resulting from GPSM1 deficiency, as revealed by glucose-tolerance tests and insulin-tolerance tests." (PMID 36434066, 2022). "Indeed, mice with the Tnfaip3 I355N allele exhibit peripheral insulin resistance and CNS inflammation, thus identifying a shared mechanism of infertility." (PMID 35464428, 2022). "To further test the idea of peripheral insulin resistance as the primary mechanism for hyperinsulinemia following glucose challenge in Tnfaip3I325N/I325N mice, we isolated and transplanted wild-type islets into Tnfaip3+/+ or Tnfaip3I325N/I325N recipients." (PMID 35464428, 2022). "It is demonstrated that the transcription of Tumor Necrosis Factor α-Induced Protein 3 (TNFAIP3) is altered, leading to the promotion of metabolic inflammation through the ablation of GPSM1 in a mouse model of high-fat diet-induced insulin resistance." (PMID 38989000, 2024).
marginal zone lymphoma (5 papers, 2013 to 2023). A usually indolent mature B-cell lymphoma, arising from the marginal zone of lymphoid tissues. "In addition, for cases with single BCL6-trans signature, the mutations in several genes were also frequently determined in marginal zone lymphoma, including NOTCH2 (14.6%, 6/41), KLF2 (34.1%, 14/41), TNFAIP3 (19.5%, 8/41), and FAS (17.1%, 7/41) mutations." (PMID 32736575, 2020). "The mutation pattern of the BN2/C1/NOTCH2 group, including mutation of NOTCH2, TNFAIP3, and BCL10 resembles that of marginal zone lymphomas (MZL) 52,53." (PMID 36788062, 2023).
ovarian tumor (5 papers, 2015 to 2025). "A20, a tumor necrosis factor α-induced protein 3 (TNFAIP3) -encoded protein characterized by an N-terminal ovarian tumor (OTU) deubiquitinase domain and seven C-terminal zinc finger (ZnF) domains, acts as a potent negative regulator of the NF-κB pathway." (PMID 40859316, 2025). "The zinc finger (ZnF) protein A20 is a ubiquitin-editing enzyme encoded by the TNFAIP3 (tumor necrosis factor a-induced protein 3) gene that contains an amino-terminal ovarian tumor (OTU) domain followed by seven ZnF domains." (PMID 37342083, 2023). "The amino terminus of TNFAIP3 contains an ovarian tumor (OUT) domain, which has DUB activity, and the carboxy terminus contains seven zinc finger (ZnF) domains that mediate ubiquitin ligase and ubiquitin‐binding activity." (PMID 36056685, 2023). "Herein, we identified a novel TNFAIP3 variation, p.(Leu236Pro), located in the A20 ovarian tumor (OTU) domain and demonstrated its pathogenicity." (PMID 37342083, 2023). "In addition, the TNFAIP3 SNPs were mainly located in exon 7 of TNFAIP3 gene in the JNU dataset, and they occurred upstream of the ovarian tumor (OTU) domain in the NFH and PRJCA002270 datasets." (PMID 36056685, 2023).
periodontitis (5 papers, 2021 to 2026). An acute or chronic inflammatory process that affects the tissues that surround and support the teeth. "Ubiquitin-editing enzyme, A20, also known as TNF-α inducible protein 3 (TNFAIP3) has emerged as a critical gatekeeper of immune homeostasis in various systemic conditions, including periodontitis, through its ability to limit inflammation." (PMID 34899728, 2021). "In periodontitis models, knocking out Tnfaip3 offset the protective effect of Mettl3 depletion." (PMID 38696610, 2024). "Furthermore, it was shown that elevated TNFAIP3 in gingival tissue is related to decreased periodontitis together with TLR9 activity." (PMID 35570325, 2022). "Therefore, the five drug molecules predicted in this study may have the potential to treat influenza A patients suffering from periodontitis by down-regulating the expression of TNFAIP3." (PMID 41592028, 2026).
allergic disease (4 papers, 2018 to 2024). An immune response that occurs following re-exposure to an innocuous antigen, and that requires the presence of existing antibodies against that antigen. "Bayesian colocalization analysis suggested that LAYN (coloc.abf‐PPH4 = 0.819) and TNFAIP3 (coloc.abf‐PPH4 = 0.930) share the same variant associated with allergic diseases." (PMID 38573314, 2024). "Next, we performed Bayesian co‐localization analysis, and the results suggested that LAYN (coloc.abf‐PPH4 = 0.819) and TNFAIP3 (coloc.abf‐PPH4 = 0.930) share the same variant with allergic diseases." (PMID 38573314, 2024). "An increase in TNFAIP3 protein levels was negatively correlated with the risk of allergic diseases, whereas an increase in LAYN protein levels was positively correlated with the risk of allergic diseases." (PMID 38573314, 2024). "The results demonstrated a significant association of TNFAIP3, IL1RL2, IL1R1, IL6R, KYNU, and ITPKA with allergic diseases in both cohorts, further supporting the reliability of the potential drug targets identified in this study." (PMID 38573314, 2024). "Our study demonstrates a causal association between the expression levels of TNFAIP3 and LAYN and the risk of allergic diseases, suggesting them as potential drug targets for these conditions, warranting further clinical investigation." (PMID 38573314, 2024). "Specifically, elevated levels of TNFAIP3, ERBB3, TLR1, and IL1RL2 proteins were associated with a reduced risk of allergic diseases, yielding corresponding odds ratios of 0.82 (0.76–0.88), 0.74 (0.66–0.82), 0.49 (0.45–0.55), and 0.81 (0.75–0.87), respectively." (PMID 38573314, 2024). "Among these, the increased levels of TNFAIP3, ERBB3, TLR1, and IL1RL2 proteins were associated with a reduced risk of allergic diseases, with corresponding odds ratios of 0.82 (0.76–0.88), 0.74 (0.66–0.82), 0.49 (0.45–0.55), and 0.81 (0.75–0.87), respectively." (PMID 38573314, 2024). "Based on MR and Bayesian co‐location analysis, we identified TNFAIP3 as a potential drug target for allergic diseases." (PMID 38573314, 2024). "Further, two proteins involved in anti-inflammatory responses and tissue repair, TNFAIP3 and MYDGF respectively, were associated with lower risk of allergy development." (PMID 33722194, 2021). "Bayesian co‐location analysis showed that TNFAIP3 and LAYN may have the same variants as allergic diseases." (PMID 38573314, 2024). "The identified proteins may serve as attractive drug targets/biomarker for allergic diseases, particularly TNFAIP3 and LAYN." (PMID 38573314, 2024). "The elevation of TNFAIP3 protein levels is associated with a reduced risk of allergic diseases, whereas the increase in LAYN protein levels is correlated with an elevated risk of allergic diseases." (PMID 38573314, 2024). "Likewise, children with higher value of Interleukin (IL)-15 as well as TNFα-induced protein 3 (TNFAIP3) and Myeloid Derived Growth Factor (MYDGF) at 1 month had lower risk to develop allergy during the 8 year follow-up period." (PMID 33722194, 2021). "Following sensitivity analysis and MR analysis, we identified two proteins among the 11 significant ones as potential drug targets for allergic diseases, namely LAYN and TNFAIP3." (PMID 38573314, 2024). "Through MR and Bayesian colocalization analysis, we identified TNFAIP3 and LAYN as potential drug targets for allergic diseases." (PMID 38573314, 2024). "However, it remains unclear whether TNFAIP3 plays a role in allergic diseases." (PMID 38573314, 2024). "In summary, we have identified four small molecular compounds that can upregulate TNFAIP3 expression and four that can downregulate LAYN expression, providing insights for targeted therapy of allergic diseases." (PMID 38573314, 2024). "TNFAIP3 and CXCL2, also related to inflammatory responses, were up-regulated at 55 min after pollen exposure and are known to be regulated in allergic diseases." (PMID 34784380, 2021).
allergic disease (continued). "Our research shows that TNFAIP3 and LAYN are potential drug targets for allergic diseases." (PMID 38573314, 2024). "This study suggests that TNFAIP3 and LAYN may serve as potential drug targets for allergic diseases." (PMID 38573314, 2024).
cervical cancer (4 papers, 2022 to 2025). A primary or metastatic malignant neoplasm involving the cervix. "A prior research demonstrated that the TNFAIP3 expression in a variety of tumors, namely, cervical cancer and liver cancer, is regulated by DNA promoter hypermethylation." (PMID 36033828, 2022). "Furthermore, OTUD5 overexpression enhanced the sensitivity of cervical cancer cells to radiotherapy, whereas TNFAIP3 knockdown decreased the sensitivity of NPC cells to radiotherapy." (PMID 40469292, 2025). "Three mutational markers (TNFAIP3, BRCA1, ASXL1) of non-responders were found to be shared with the DNA markers from patients with progressive disease in an independent cervical cancer cohort (GEO repository: GSE205247)." (PMID 38951894, 2024).
Cirrhosis (4 papers, 2019 to 2025). A chronic disorder of the liver in which liver tissue becomes scarred and is partially replaced by regenerative nodules and fibrotic tissue resulting in loss of liver function. "The present study revealed that deleterious variants in TNFAIP3 were predisposing for AIH with cirrhosis in a Japanese population." (PMID 31138864, 2019). "The deleterious variants in the coding regions of TNFAIP3 gene were analyzed by the cycle sequencing method and the frequencies of deleterious TNFAIP3 alleles of AIH or AIH with cirrhosis were compared with those of Japanese controls." (PMID 31138864, 2019). "We investigated deleterious variants in the coding regions of TNFAIP3 gene of Japanese AIH patients or those with cirrhosis." (PMID 31138864, 2019). "However, deleterious variants in TNFAIP3 have been reported to predispose patients to AIH with cirrhosis, with one report of death from progressive liver disease with cirrhosis, necessitating careful follow-up when liver dysfunction is observed." (PMID 40574834, 2025). "Deleterious variants in TNFAIP3 were revealed to be risk factors for AIH with cirrhosis." (PMID 31138864, 2019). "A significant association was shown for the deleterious alleles in TNFAIP3 (P = 0.0180, odds ratio (OR) 4.28, 95% confidence interval (CI) 1.53–11.95) with AIH with cirrhosis at presentation." (PMID 31138864, 2019). "Thus, we investigated the variants in the coding regions of TNFAIP3 gene of Japanese AIH patients by the cycle sequencing method and tried to compare the frequencies of deleterious TNFAIP3 alleles of AIH or AIH with cirrhosis with those of Japanese controls." (PMID 31138864, 2019). "Additionally, the proportion of CD4 T cell-TNFAIP3, CD8 T cell-TNF (effector CD8 T cells), and CD8 T cell-CD53 increased, while the proportion of Treg cells decreased from HBV infection to cirrhosis." (PMID 38116005, 2023).
juvenile idiopathic arthritis (4 papers, 2013 to 2021). Juvenile idiopathic arthritis (JIA) is the term used to describe a group of inflammatory articular disorders of unknown cause that begin before the age of 16 and last over 6 weeks. "Strong associations were observed between TNFAIP3 rs10499194 and juvenile idiopathic arthritis (OR = 0.74, 95% CI = 0.61–0.91, p < 0.004)." (PMID 28702029, 2017).
non-Hodgkin lymphoma (4 papers, 2016 to 2024). Distinct from Hodgkin lymphoma both morphologically and biologically, non-Hodgkin lymphoma (NHL) is characterized by the absence of Reed-Sternberg cells, can occur at any age, and usually presents as a localized or generalized lymphadenopathy associated with fever and weight loss. "Loss of TNFAIP3 enhances MYD88L265P-driven signaling in non-Hodgkin lymphoma, presenting a potential opportunity for therapeutic targeting." (PMID 38313801, 2024). "A number of studies have reported the deletions or mutations of TNFAIP3 (encoding gene of A20) in lymphomas such as marginal zone lymphoma and Non-Hodgkin’s lymphoma, indicating A20 as a tumor suppressor and immune regulator." (PMID 28031783, 2016). "On this basis, genetic variants of genes implicated in the regulation of chronic inflammation such as TNFAIP3 –, and LILRA3, B cell activation, type I IFN pathways such as TREX-1 as well as epigenetic processes have been shown to increase the risk of Non-Hodgkin Lymphoma (NHL) in SS." (PMID 35402956, 2020).